MRPS25 (mitochondrial ribosomal protein S25)
Synonyms: MRP-S25; RPMS25; FLJ00023; DKFZp313H0817; mS25; COXPD50
Tractability: Small molecule: a structure with a bound ligand is known. PROTAC: ubiquitination databases record sites on it; its protein half-life has been measured.
Gene: Protein-coding gene on chromosome 3 (15,009,611 to 15,065,339, reverse strand). Ensembl gene ENSG00000131368.
Subcellular location: Mitochondrion
Subcellular location (Human Protein Atlas): Mitochondria
Pathways (Reactome):
Metabolism of proteins: Mitochondrial ribosome-associated quality control; Mitochondrial translation elongation; Mitochondrial translation initiation; Mitochondrial translation termination
Gene Ontology:
Molecular function: structural constituent of ribosome
Biological process: mitochondrial translation
Cellular component: mitochondrion; mitochondrial inner membrane; mitochondrial small ribosomal subunit
Genetic constraint (gnomAD): Loss-of-function variants: 13 observed, 17.28 expected, observed/expected ratio (o/e) 0.75, 90% interval 0.49 to 1.2. The upper end of that interval is the gene's LOEUF score, 1.2, which puts it in group 5 of 6, group 1 being the genes least tolerant of losing a copy. Missense variants: 221 observed, 219.76 expected, observed/expected ratio (o/e) 1.01, 90% interval 0.9 to 1.12. Synonymous variants: 90 observed, 82.12 expected, observed/expected ratio (o/e) 1.1, 90% interval 0.92 to 1.31.
Gene-disease validity (ClinGen):
ClinGen rates the evidence that MRPS25 causes each of these diseases.
mitochondrial disease (autosomal recessive): Limited.
Homologues: Orthologues: chimpanzee MRPS25 (100% identical), macaque MRPS25 (97% identical), pig MRPS25 (92% identical), dog MRPS25 (91% identical), mouse Mrps25 (88% identical), guinea pig MRPS25 (87% identical), rat Mrps25 (87% identical), rabbit MRPS25 (82% identical), tropical clawed frog mrps25 (78% identical), zebrafish mrps25 (73% identical), Drosophila melanogaster mRpS25 (54% identical), Caenorhabditis elegans mrps-25 (38% identical).
Diseases named in the same sentence as MRPS25 in open-access papers:
MRPS25 is named in the same sentence as 8 diseases in open-access papers, as found by Europe PMC text mining. Sharing a sentence is not in itself a finding about the gene and the disease. The quoted sentences say what the papers report.
Encephalopathy (2 papers, 2021 to 2024). Encephalopathy is a term that means brain disease, damage, or malfunction. "Two of these genes, MRPS22 and MRPS25, are implicated in human hypertrophic cardiomyopathy and encephalopathy, although the exact functions of this gene cluster in muscle development need further study." (PMID 39014195, 2024). "mS25 (MRPS25)—The mutation c.215C > T (p.P72L) in mS25 was identified in an individual presenting with encephalopathy, short stature, microcephaly, and dystonia." (PMID 33917098, 2021).
brain disorder (1 paper, 2024). A disease affecting the brain or part of the brain. "We found 7 variants that were associated with neurodevelopment and brain disorders, of which, 4 variants were found in both patients, namely in genes CTBP2, CDC27, UNC13D and IRF8, and 3 variants found in either of the patients, NDUFAF3, MRPS25, MORC3." (PMID 38638145, 2024).
mitochondrial disease (1 paper, 2022). "Mitochondrial disease-causing mutations were found in thirteen small ribosomal subunit mitoribosomal proteins (MRPS1, MRPS2, MRPS6, MRPS7, MRPS9, MRPS11, MRPS14, MRPS16; MRPS22, MRPS23, MRPS25, MRPS34, MRPS39) and four large ribosomal mitochondrial proteins (MRPL3, MRPL12, MRPL24, MRPL44)." (PMID 36140315, 2022).
MRPS25 also shares sentences with these, for which no sentence is quoted: encephalomyopathy (2 papers); Dystonia (1); hypertrophic cardiomyopathy (1); lactic acidosis (1); schizophrenia (1).